MIR520C (microRNA 520c)
Synonyms: hsa-mir-520c; MIRN520C
Gene: MicroRNA gene on chromosome 19 (53,707,453 to 53,707,539, forward strand). Ensembl gene ENSG00000207738.
Gene Ontology:
Biological process: miRNA-mediated post-transcriptional gene silencing
Homologues: Orthologues: chimpanzee ptr-mir-520c (100% identical), macaque MIR520C (90% identical). Paralogues in human: MIR516A1 (92% identical), MIR516A2 (91% identical), MIR519A2 (90% identical), MIR519C (90% identical), MIR520F (90% identical), MIR516B1 (89% identical), MIR522 (89% identical), MIR523 (89% identical), MIR520E (87% identical), MIR518C (86% identical), MIR518D (86% identical), MIR518E (86% identical), and 12 more.